ATP7B (ATPase copper transporting beta)
Diseases named in the same sentence as ATP7B in open-access papers (continued):
Sharing a sentence is not in itself a finding about the gene and the disease.
esophageal cancer (1 paper, 2021). A primary or metastatic malignant neoplasm involving the esophagus. "Nonetheless, our results completes the previous observation that esophageal cancers expressing the P-type ATPase ATP7B, a platinum exporter, are more resistant to cisplatin than ATP7B-negative tumors." (PMID 34603016, 2021).
gastric adenocarcinoma (1 paper, 2023). "After searching the COSMIC database, only one of the variants (c.4232G>A; ATP7B) has been found in adenocarcinomas - in gastric adenocarcinoma." (PMID 37427132, 2023).
glioblastoma (1 paper, 2023). The most malignant astrocytic tumor (WHO grade IV). "The ATP7B gene was involved in glioblastoma resistance to temozolomide." (PMID 38037104, 2023).
laryngeal squamous cell carcinoma (1 paper, 2022). A squamous cell carcinoma that arises from the larynx. "For example, increased NFE2L2 and TMB pathway changes were linked to radiation resistance in laryngeal squamous cell carcinoma (LSCC), and NLRP3 activation could promote carcinogenesis and chemoresistance in HNSCC, and ATP7B upregulation promoted chemoresistance of HNSCC." (PMID 36620545, 2022).
liver steatosis (1 paper, 2022). "In our hands, Ole, in presence of liver steatosis, was able to further increase the expression levels of CTR1 and ATP7B, let thinking that a higher Cu-dependent antioxidant activity may be induced by the treatment with the nutraceuticals compound." (PMID 35148806, 2022). "Interestingly, in our mouse model were both altered in presence of liver steatosis, together with the influx and efflux Cu-transporter proteins: CTR1 and ATP7B." (PMID 35148806, 2022).
melanoma (1 paper, 2022). A malignant, usually aggressive tumor composed of atypical, neoplastic melanocytes. "Moreover, we detected that PD-L1 expression was positively correlated with some cuproptosis-related genes (CDKN2A, FDX1, LIPT1, and MTF1), but negatively correlated with other cuproptosis-related genes (ATP7B, DLST, and PDHA1) in an analysis of 470 melanoma patients." (PMID 35837286, 2022).
mucinous tumors (1 paper, 2021). "ATPase copper transporting beta (ATP7B) was mutated in 8.96% of mucinous tumors compared with only 3.45% of non-mucinous tumors." (PMID 33808549, 2021).
non-small cell lung carcinoma (1 paper, 2025). A group of at least three distinct histological types of lung cancer, including non-small cell squamous cell carcinoma, adenocarcinoma, and large cell carcinoma. "Researchers have also reported that combining the apoptosis inducer disulfiram with anti-PD-L1 effectively overcomes drug resistance in non-small cell lung cancer (NSCLC) by regulating the ATP7B-mediated HIF-1 signaling pathway." (PMID 40406488, 2025).
ovarian tumor (1 paper, 2022). "This indicates that the ability of TFEB to upregulate ATP7B expression in response to cisplatin might contribute to the chemoresistance of different ovarian tumor cell lines." (PMID 35053335, 2022).
prion disease (1 paper, 2014). A transmissible disease that is caused by a protein that is able to induce abnormal folding of normal cellular proteins, leading to characteristic spongiform brain changes, which are associated with neuronal loss without an inflammatory response. "We describe a case of severe, rapidly progressive neurological WD in a patient who was found to carry heterozygous allelic variants in the two genes (ATP7B and PRNP) that have been linked to WD and prion disease, respectively." (PMID 24555712, 2014). "Based upon the patient’s history of a severely progressive neurological disorder with basal-ganglia symptoms/signs, ataxia and a major antecedent psychiatric presentation, diagnoses of either WD or genetic prion disease were considered, and DNA sequence analysis of ATP7B and PRNP was requested." (PMID 24555712, 2014).
Subcutaneous lipoma (1 paper, 2024). The presence of subcutaneous lipoma. "In addition, Schaefer reported that the formation of subcutaneous lipomas in patients with WD may be associated with mutations in an adjacent region of the ATP7B gene." (PMID 38273263, 2024).
tumor (62 papers, 2005 to 2026). "GW4869 did not affect the in vivo tumor growth but caused a reduction in the ATP7B expression in tumor tissues." (PMID 41107546, 2026). "Although functional analyses revealed that ATP7B plays tumor-suppressive roles in BC cells, elucidating the underlying mechanism remains a difficult task." (PMID 40316883, 2025). "Elevated ATP7B expression and its post-Golgi trafficking have been linked to tumor cell resistance to Pt-based chemotherapy." (PMID 40406488, 2025). "The copper-transporting P-type ATPases ATP7A and ATP7B are both expressed in the cochlea-ATP7A localizes predominantly to pillar cells of the organ of Corti, whereas ATP7B is found in hair cells-and have been implicated in tumor resistance to platinum drugs." (PMID 41169615, 2025). "Correspondingly, TFEB suppression results in reduced ATP7B expression and elevated susceptibility of tumor cells to cisplatin." (PMID 35053335, 2022). "This indicates that Tranilast targets ATP7B-mediated resistance mechanism in a tumor-specific manner, which would strongly reduce the risk of side effects and adverse events upon therapeutic use." (PMID 32155756, 2020). "Although ATP7A and ATP7B are important effectors of Cu homeostasis in the body, overexpression of both proteins has been found to be associated with tumor resistance to cisplatin during chemotherapy." (PMID 31540259, 2019). "Altered ATP7B expression in cancer is also associated with tumor progression and drug resistance." (PMID 40406488, 2025). "It has been demonstrated repeatedly that higher expressions of ATP7B are associated with tumor resistance to cisplatin, although the exact mechanism is unknown." (PMID 37427132, 2023). "Kaplan–Meier and Cox proportional hazards regressions were used to estimate prognostic factors associated with ATP7B.The correlations between the expression of ATP7B and immune cell infiltration, tumor mutation burden, microsatellite instability and immune checkpoint molecules were analyzed." (PMID 38037104, 2023). "Indeed, increased expression of the Golgi-localized Cu-transporting ATPases, ATP7A and ATP7B, have been associated to tumor aggressiveness as well as chemo-resistance." (PMID 33015030, 2020). "Another important issue that has to be taken into account is that suppression of either ATP7A or ATP7B, which is desirable in tumors, might cause significant side effects in extra-tumor tissues." (PMID 31540259, 2019). "The positive correlation between ATP7B and activated mast cells (cor = 0.38), along with the negative correlation between activated mast cells and risk score, suggests that ATP7B may influence the tumor immune microenvironment by modulating mast cell activation." (PMID 41278297, 2025). "To comprehensively evaluate how the ATP7B-correlated protein profile in HNSC contributes to CDDP resistance, we used the LinkedOmics database to examine ATP7B co-expressed proteins in normal and tumor tissues from the CPTAC-HNSC cohort." (PMID 41107546, 2026). "Heatmaps of the top 50 proteins that were positively correlated with ATP7B in normal tissues and tumor tissues were also created." (PMID 41107546, 2026). "The effect of the RBM15/m6A/SRSF1/ATP7B axis on tumor growth was evaluated using tumor xenografts in nude mice." (PMID 40923717, 2026). "In the normal tissues, TGN markers showed a significantly strong positive correlation with ATP7B expression, whereas in the tumor tissues, the correlation was clearly attenuated." (PMID 41107546, 2026). "Further histopathological analysis revealed that the livers of Atp7b−/− mice contained extensive areas of proliferating biliary ducts forming tumor-like nodes." (PMID 39922819, 2025). "In this context, researchers have identified a novel transcriptional mechanism that regulates ATP7B expression in drug-resistant tumor cells through Pt-dependent transcription factor EB (TFEB) activation." (PMID 40406488, 2025).
tumor (continued). "In this study, ATP7B interfered with tumor progression by suppressing the proliferation, invasiveness, and migration of BC cells." (PMID 40316883, 2025). "ATP7B is involved in promoting anti-cancer activities of tumor suppressors in BC cells across different subtypes and is considered a prognostic marker for BC." (PMID 40316883, 2025). "An analysis of ATP7B expression difference on drug sensitivity on tumor cells was performed using the CTRP, GDSC and CMap database." (PMID 38037104, 2023). "We evaluated the biological significance of differentially expressed ATP7B markers using GESA analysis in various tumor tissues." (PMID 38037104, 2023). "The HPA database contains millions of immunohistochemical images that we used to compare ATP7B protein expression between normal and tumor tissues." (PMID 38037104, 2023). "In conclusion, targeting Copper-transporting ATPases,ATP7A or ATP7B,has broad application space in overcoming the resistance of tumor cells to platinum drugs." (PMID 36925927, 2023). "Using the Cancer Genome Atlas (TCGA), we examined how ATP7B expression correlated with prognosis and stage among different tumor types." (PMID 38037104, 2023). "ATP7B is not only involved in tumour progression, but also in the development of platinum drug resistance." (PMID 38259456, 2023). "Nine CRGs were differentially expressed between tumor and normal tissues, among which NFE2L2, SLC31A1, FDX1, DLD, DLAT, and DLST were lowly expressed in tumor tissues, and ATP7B, CDKN2A, and GCSH were highly expressed in tumor tissues (p<0.05)." (PMID 37205181, 2023). "As a result, we will be able to develop a novel anti-tumor treatment program for cancer by clarifying the mechanism of ATP7B in inflammatory-related activities." (PMID 38037104, 2023). "Cancer cells expressed significantly more ATP7B than non-tumor cells in seven types of cancer: BRCA, COAD, KIRC, PRAD, READ, STAD, UCEC." (PMID 38037104, 2023). "Our previous studies suggest that ATP7B provides a significant contribution to Pt-tolerance that was observed in tumor cells of ovarian origin." (PMID 35053335, 2022). "This property of ATP7B is particularly relevant in oncology because both elevated ATP7B expression levels and its post-Golgi trafficking have been shown to correlate with tumor cell resistance to Pt-based chemotherapy." (PMID 35053335, 2022). "The results showed that, in tumor samples, ATP7B, PDHA1, and SLC31A1 were significantly upregulated compared with normal tissues, whereas ATP7A, DLST, GCSH, LIAS, and LIPT1 were significantly downregulated." (PMID 36567939, 2022). "The expression of MTF1, NLRP3, and SLC31A1 was positively related with ImmuneScore, StromalScore, and ESTIMATEScore in almost all types of tumor, whereas ATP7B, DLAT, DLD, LIAS, PDHA1, and PDHB were significantly negatively correlated with the scores." (PMID 36387247, 2022). "In this context, our findings shed light on a new transcription mechanism that regulates ATP7B expression in resistant tumor cells through Pt-dependent activation of TFEB." (PMID 35053335, 2022). "Increased resistance to platinum-based chemotherapy has been related to an increase in the expression of ATP7B in tumor cells." (PMID 36092880, 2022). "Our study revealed that ATP7B was up-regulated in tumor tissues, and patients who expressed high levels of ATP7B had a poor prognosis." (PMID 36567939, 2022). "It is highly likely that TFEB-mediated transactivation of ATP7B is used as a Pt defense mechanism by different tumor cells." (PMID 35053335, 2022). "Conversely, ATP7B is involved in the efflux and sequestration of cisplatin, thereby increasing the resistance of tumor cells to platinum treatment." (PMID 36713586, 2022). "In this regard, Pt-dependent mechanisms that regulate ATP7B expression in tumor cells are of great importance and have to be better understood." (PMID 35053335, 2022).
tumor (continued). "A growing body of evidence indicates that ATP7B is used by malignant cells to detoxify platinum (Pt)-based drugs, thereby promoting tumor resistance to chemotherapy." (PMID 35053335, 2022). "The ability of the drug hits to promote cisplatin toxicity was also confirmed on the other ATP7B-mediated resistant tumor cell line A2780-CP20." (PMID 32155756, 2020). "All three drugs induced Pt-mediated DNA damage and inhibited either expression or trafficking of ATP7B in a tumor-specific manner." (PMID 32155756, 2020). "By harboring the Cu-transporting ATPases ATP7A and ATP7B, the Golgi regulates the supply of Cu to several oncogenic metalloenzymes and the overall availability of Cu in tumor cells." (PMID 31540259, 2019). "In this review, we discuss how the ability of the Golgi resident transporters ATP7A and ATP7B to handle Cu and Pt enables malignant cells to protect themselves from cisplatin-mediated death and to promote tumor growth and invasion." (PMID 31540259, 2019). "Immunostaining of oxaliplatin transporters (OCT1, 2, 3, CTR1 and ATP7B) and Ki-67 was assessed in tumor samples." (PMID 26859833, 2016). "Some transporters like Ctr1 and ATP7B seem to be involved in determining general sensitivity of tumor cells against platinum-based chemotherapy." (PMID 24278698, 2012). "Available information consistently provided strong evidence that ATP7B mediates resistance to platinum drugs by regulating drug efflux, and tumours with higher ATP7B expression did show an unfavourable response to platinum drug treatment." (PMID 17609664, 2007). "There was a paradoxical decrease in the copper export pump ATP7B following cisplatin exposure, in tumor-derived breast cells (p = 0.0327, Wilcoxon matched pairs test), but not in ovarian cells." (PMID 16026610, 2005). "However, the immunohistochemical staining of the resected tumor specimens demonstrated that the expression of ATP7B was significantly increased in the GW4869-treated group compared to the control group." (PMID 41107546, 2026). "However, the enrichment analysis of the CPTAC-HNSC cohort showed that Golgi-localized proteins positively correlated with ATP7B expression were upregulated in normal tissues but disappeared in tumor tissues." (PMID 41107546, 2026). "Research indicates that ATP7B can influence the resistance to copper-based anticancer agents, as some tumor cells may upregulate ATP7B to expel intracellular copper, thereby reducing the cytotoxicity of these drugs." (PMID 40406488, 2025). "In addition, ATP7A and ATP7B are also involved in regulating the transport of platinum-based drugs within tumor cells." (PMID 40013141, 2025). "Although no studies to date have suggested a direct relationship between ATP7B and these molecules, ATP7B may affect the expression of these genes to suppress tumor progression in BC." (PMID 40316883, 2025). "In conclusion, this study revealed the tumor-suppressive roles of ATP7B in BC cells." (PMID 40316883, 2025). "The reduced DNMT1 protein levels, increased unmethylated promoter amounts, increased miR‐302a‐3p levels, and reduced ATP7B mRNA levels in PLB‐treated tumor samples further support that the DNMT1/miR‐302a‐3p/ATP7B axis mediated cuproptosis triggered by PLB in vivo." (PMID 40761482, 2025). "Thus, we inferred that the results of in vitro cell experiments are similar to those of ATP7B knockout mice, while the results of in vivo tumor experiments are similar to those of mice in which only ATP7B is lost in hepatocytes." (PMID 39198750, 2024). "This implies that altering the Cu levels of tumor cells could be a viable approach to modulate ATP7B expression and counter cancer cell resistance to cisplatin." (PMID 38918694, 2024). "Besides Cu transport, ATP7A and ATP7B can interact with platinum drugs and pump them across membranes, contributing to the resistance of tumor cells to platinum-based cancer treatments." (PMID 38918694, 2024).
tumor (continued). "We speculated that the increase in the expression levels of ACO2 and SDHB is related to the decrease in ATP7B in tumor tissues." (PMID 39198750, 2024). "Besides, ATP7A and ATP7B can interact with platinum drugs and pump them across membranes, contributing to the resistance of tumor cells to platinum-based cancer treatments." (PMID 38918694, 2024). "From this, we deduce that ATP7B participates in tumor development and tumorigenesis." (PMID 38037104, 2023). "A comprehensive examination of ATP7B expression in various tumor types was conducted in our study." (PMID 38037104, 2023). "We reasoned that a cohort of TFEB target genes might include ATP7B, whose elevated expression confers Pt-resistance in tumor cells." (PMID 35053335, 2022). "A similar ATP7B-dependent mechanism has been proposed to reduce Pt toxicity in tumor cells." (PMID 32155756, 2020). "The drugs act via several mechanisms including the tumor-specific suppression of ATP7B expression and trafficking and the downregulation of large cohorts of genes that belong to cisplatin-resistance pathways including DNA repair, protein quality control, and autophagy." (PMID 32155756, 2020). "In agreement with this hypothesis, extensive relocation of ATP7B from the Golgi to vesicular compartments was observed in Pt-resistant tumor cells." (PMID 32155756, 2020). "Indeed, silencing ATP7B has been demonstrated to reduce tolerance of tumor cells to Pt-based drugs in vitro and in vivo." (PMID 32155756, 2020). "Additionally, the same Golgi-resident transporters ATP7A and ATP7B are also capable of pumping Pt across membranes rendering the tumor cells resistant to Pt-based cancer therapy." (PMID 31540259, 2019). "Therefore, the presence of ATP7A and ATP7B in these structures suggests that both proteins traffic to LEs/lysosomes in Pt-resistant tumor cells." (PMID 31540259, 2019). "Suppression of these proteins in Pt-resistant tumor cells might affect ATP7B trafficking and hence tolerance to cisplatin chemotherapy." (PMID 31540259, 2019). "It is tempting to speculate that similar endo-lysosomal structures use ATP7B to sequester Pt in tumor cells." (PMID 31540259, 2019). "Considering that ATP7A/B function can facilitate tumor invasiveness and resistance to chemotherapy, many lessons from disease-causing ATP7A and ATP7B mutants could be learned to activate mechanisms that promote their loss of function in tumors." (PMID 31540259, 2019). "Notably, a recent study demonstrates that Cu chelator tetrathiomolybdate inhibits platination of ATP7B via dimerization of MBSs, hence, rendering the protein less capable of driving Pt efflux from tumor cells." (PMID 31540259, 2019). "In addition, our study found that EGCG down-regulated the expression of MTF1 and ATP7B, but was not affected by copper, that is, EGCG treatment alone was capable of down-regulating the expression of ATP7B without causing cuproptosis in cells or tumor tissues." (PMID 40136640, 2025). "Targeting ATP7A/ATP7B could increase tumor cell sensitivity to platinum drugs." (PMID 38918694, 2024). "Additionally, ATP7A and ATP7B also produce a marked effect in tumor progression." (PMID 36925927, 2023). "This review summarizes current data on the role of ATP7A/B in the regulation of Cu and Pt metabolism in malignant cells and outlines questions and challenges that should be addressed to understand how ATP7A and ATP7B trafficking mechanisms might be targeted to counteract tumor development." (PMID 31540259, 2019). "Furthermore, they demonstrated that exogenous miR-133a, which through induction of apoptosis and inhibition of tumor cell metastasis functions as a tumor inhibitor, reduced ATP7B expression significantly in HEP-2v cells and concomitantly lowered cell viability after cisplatin treatment." (PMID 30071606, 2018).